STAT3 (signal transducer and activator of transcription 3)
Diseases named in the same sentence as STAT3 in open-access papers (continued):
Sharing a sentence is not in itself a finding about the gene and the disease.
breast cancer (continued). "Silencing STAT3 using the PR39/STAT3 siRNA complexes also decreased the expression of MMP9 in breast cancer cells, which might explain the decrease in their migration potential." (PMID 38067351, 2023). "Therefore, PRRG4 via STAT3 likely promotes mitochondrial biogenesis and oxidative phosphorylation to enhance the migration of breast cancer cells." (PMID 38102641, 2023). "Our results suggested that MLN8237 and STAT3 inhibitors jointly treated breast cancer strategies may enhance antitumor immunity reaction by inhibiting tumor cell proliferation and metastasis." (PMID 37781397, 2023). "In addition, signal transducer and activator of transcription 3 (STAT3) is constitutively activated in a wide variety of solid tumours including breast cancer, prostate cancer, CRC, melanoma, and brain cancer." (PMID 36857852, 2023). "Interestingly STAT3 and ERK signaling that we observed being stimulated by GROα have been implicated in treatment resistance in HR+ breast cancer." (PMID 37423299, 2023). "The dynamic expression and activation of Stat3 and Src during the response to tamoxifen suggests that inhibiting these proteins might prevent breast cancer cell survival and the development of tamoxifen resistance." (PMID 36266450, 2023). "Using a Bcl-2 antagonist (sabutoclax) could inhibit the IL-6/STAT3 signaling to resensitize Dox-resistant breast cancer in vitro and in vivo models." (PMID 37480115, 2023). "Enhanced Stat3 activity has been reported in established endocrine-resistant breast cancer cell models compared to endocrine-sensitive cells, leading to the testing of several Stat3 inhibitors in cell line and PDX models of endocrine-resistant and sensitive breast cancer." (PMID 36266450, 2023). "Furthermore, in obese mice with spontaneous onset of mammary tumors, ablation of T-cell STAT3, or treatment with FAO inhibitors, reduced FAO to increase glycolysis and CD8+ T effector cell function, thereby inhibiting mammary tumor development." (PMID 37422501, 2023). "Curcumin, the principal curcuminoid found in turmeric, has been shown to inhibit STAT3 activity in multiple cancer types, including lung, renal, gastric, melanoma, pancreatic, ovarian, prostate, colorectal, and breast cancers, resulting in attenuated cell growth both in vitro and in vivo." (PMID 37173951, 2023). "ILEI has been shown to act via the LIFR/ STAT3 axis to mediate EMT in breast cancer stem cells." (PMID 37226685, 2023). "Moreover, we found that the level of phosphorylated STAT3 (p-STAT3) increased significantly in breast cancer cells cultured with CAF CM." (PMID 36635302, 2023). "While there is no clear link between elements of ERBB-signaling and STAT3 during involution, there is evidence from multiple breast cancer lines that ERBB2-ERBB3 heterodimers can activate STAT3 upon NRG binding, in a signaling network that also involves the PR and the ERK1/2 pathway." (PMID 37219601, 2023). "Moreover, tocilizumab (the inhibitor of IL-6 receptor) can inhibit the cancer-promoting effect of CAFs in breast cancer by inhibiting the STAT3/AU-rich element RNA-binding protein 1 (AUF1) pathway." (PMID 37666813, 2023). "STC1, Stanniocalcin 1, it has been found to promote metastasis, lipid metabolism and cisplatin chemoresistance in ovarian cancer, STC1 is mainly involved in STAT3-mediated proliferation in breast cancer and STC1 expression is thought to play an important role in driving tumor immune resistance." (PMID 38033866, 2023). "Mechanistically, PRRG4 via Src activated STAT3 in breast cancer cells." (PMID 38102641, 2023). "Furthermore, TAMs induce doxorubicin resistance in breast cancer by upregulating IL-10 via the IL-10/IL10-receptor/STAT3/Bcl-2 signaling pathway." (PMID 37369757, 2023). "Next, we investigated whether STAT3 mediates PRRG4-enhanced migratory behaviors of breast cancer cells by performing transwell migration and invasion assays." (PMID 38102641, 2023).
breast cancer (continued). "In the mouse breast cancer xenograft model, the treatment of CaP@HA loaded with the STAT3 ODN-decoy plus TRAZ inhibited tumor growth and induced tumor cell apoptosis to a greater extent than the application of a naked oligonucleotide therapeutic in combination with TRAZ or TRAZ alone." (PMID 38067351, 2023). "A recent study revealed that MORC4 might confer increased chemoresistance to breast cancer cells via STAT3-mediated MID2 upregulation." (PMID 37760252, 2023). "We also determined the changes in the IL6 and STAT3 levels in mammary tumors." (PMID 36980301, 2023). "Indeed, increasing evidence has shown that STAT3 is constitutively activated in 82% of prostate cancers, 70% of breast cancers, over 90% of head and neck cancers, and more than 50% of lung cancers." (PMID 37298475, 2023). "A previous study showed that MUC1 interacts with STAT3 directly in breast cancer." (PMID 36810913, 2023). "However, the combination of dim light at night (dLAN) results in the activation of STAT3, which is often overexpressed in paclitaxel-resistant breast cancer." (PMID 37190065, 2023). "Previous study demonstrated that Tregs Foxp3 expression level was directly connected to the level of STAT3 in skeletal immune system and breast cancer, and STAT3 activity is also correlated with poor prognosis in EC patients who had undergone surgical resection or chemoradiotherapy." (PMID 36226375, 2023). "Moreover, the pSi-STAT3-treated 4T1 breast cancer cells indicated a reduced potential for induction angiogenesis and migration." (PMID 38067351, 2023). "Moreover, the percentage of breast cancer cells expressing CD44high/CD24low, as well as the protein and transcript levels of signal transducer and activator of transcription 3 (STAT3) and IL-6, are reduced by catechol treatment." (PMID 36902427, 2023). "Moreover, we revealed that patients with breast cancer with high levels of p-STAT3 had significantly worse disease-free survival compared to those with low levels of p-STAT3." (PMID 36635302, 2023). "Since STAT3 is a transcription factor, we hypothesized that STAT3 promotes POLG transcription in breast cancer cells." (PMID 38102641, 2023). "Another in vitro study using MDA-MB-231 breast cancer cells resistant to chemo- and radiotherapy has shown that the STAT3 ODN-decoy could restore cell sensitivity to treatment." (PMID 38067351, 2023). "Of note, apart from promoting an immune-suppressive tumor microenvironment, STAT3 signaling in breast cancer cells not only contributes to proliferation and metastatic behavior but also mediates immune evasion and resistance to cyclin-dependent kinase inhibitors (CDKi)." (PMID 36980181, 2023). "Compared with vector only, PRRG4-WT enhanced p-STAT3 levels in breast cancer cells." (PMID 38102641, 2023). "Importantly, HDAC4-related inhibitors can inhibit the activation of downstream IL-6/STAT3 signaling to suppress the growth and metastasis of breast cancer." (PMID 37843550, 2023). "STAT3 siRNA was delivered into 4T1 breast cancer cells using the pGensil-2 plasmid (pSi)." (PMID 38067351, 2023). "Interestingly, a positive correlation has been reported between miR-182-5p and the Stat3 pathway in gliomas and breast cancer." (PMID 37887350, 2023). "The knockdown of FTO or STAT3 decreased doxorubicin resistance, which could be a potential strategy in the treatment of breast cancer." (PMID 37264402, 2023). "Phosphorylation of STAT3 favors breast cancer progression and activates HIF-1α." (PMID 36674719, 2023). "Our findings on the roles of STAT3 and STAT1 in mediating PD-L1 activities in breast cancer indicate that STAT3 and STAT1 cannot act independently from each other, and suggest that intersections exist between these two transcription factors in mediating PD-L1-induced effects." (PMID 37830552, 2023).
breast cancer (continued). "The JAK2/STAT3 signaling pathway is required for growth of CD44(+) CD24(−) stem cell-like breast cancer cells, particularly in basal-like breast cancers and is independently associated with breast cancer metastasis and poor prognosis." (PMID 36635351, 2023). "Carnitine palmitoyltransferase 1B (CPT1B) exerts rate-controlling-enzyme roles in fatty acids β-oxidation, could be inhibited by inhibiting JAK/STAT3 promoting breast cancer cells to re-sensitize to chemotherapy." (PMID 37221577, 2023). "Thus, in patients with breast cancer, a poor response to radiotherapy correlates with IL-6 and p-STAT3 levels." (PMID 36635302, 2023). "The silencing of STAT3 by shRNA in HER2 overexpressing breast cancer cells resulted in a reduction in CD44-positive cells and the downregulation of the expression of stem cell markers, such as Octamer-binding transcription factor (OCT-4) and SRY (sex determining region Y)-box 2 (SOX-2)." (PMID 38067351, 2023). "Stat3 has been gaining momentum as an important player in breast cancer progression." (PMID 36266450, 2023). "Inhibiting the ERK/STAT3 signaling pathway could inhibit the growth of breast cancer and the formation of a large number of blood vessels and eliminating the lactate-induced polarization of M2 macrophages." (PMID 36709284, 2023). "Moreover, ADAM12 significantly upregulated pro-angiogenic factors and increased endothelial cell recruitment in a STAT3-dependent manner to promote tumor angiogenesis in breast cancer." (PMID 36717944, 2023). "PIN1 also enhances STAT3-mediated EMT induced by Oncostatin M in breast cancer cells." (PMID 36813923, 2023). "Similarly, cucurbitacin D inhibits cell growth and induces apoptosis through inhibition of STAT3 activity in breast cancer cells." (PMID 37887406, 2023). "Also, TrkB induces cell survival of colon and breast cancer through the activation of ERK or JAK2/STAT3 signaling pathways." (PMID 37749450, 2023). "Signal transducer and activator of transcription 3 (STAT3)-YAP/TAZ (transcriptional coactivator with PDZ-binding motif) signaling also promotes angiogenesis and is associated with poor survival in breast cancer." (PMID 37173920, 2023). "Additionally, via the NF-kB/IL-6/JAK2/STAT3 pathway inhibition in breast cancer cells, we recently demonstrated the anticancer activity of azilsartan." (PMID 36611978, 2023). "In addition, PRRG4-mediated activation of STAT3 also enhanced filopodia formation, migration, and invasion of breast cancer cells." (PMID 38102641, 2023). "To date, research has unequivocally shown that STAT3 overexpression in breast cancer tissue may be beneficial in terms of patient outcomes." (PMID 37371647, 2023). "Furthermore, an interplay between the NF-κB pathway and STAT3 has been observed, as they collaboratively participate in the regulation of hTERT expression in breast cancer cells." (PMID 37612721, 2023). "CypA/CD147 activation is essential for maintaining CSC features in breast cancer cells through signal transducer and activator of transcription 3 (STAT3) signaling, such as their tumorsphere-forming ability, the expression of stemness markers, and chemoresistance." (PMID 36902161, 2023). "However, more recent research has shown that IL-6 activates STAT3 in ER-expressing breast cancer cells and increases its invasive and metastatic activity." (PMID 37834225, 2023). "Interestingly, in a study of breast cancer, STAT3 was shown to be an upstream regulator of Notch, and inhibition of this signaling pathway inhibited macrophage M2 polarization and thus breast cancer metastasis." (PMID 37081874, 2023). "This study illustrates that phosphorylated STAT3 may be involved in breast cancer cell proliferation and progression." (PMID 37450039, 2023). "In addition, as a natural polyphenol, STAT3 can be degraded by ROS-dependent proteasome to inhibit the migration, metastasis, and tumor growth of breast cancer." (PMID 37509109, 2023).
breast cancer (continued). "The overexpression of oncogene products also contributes to paclitaxel resistance, among which the transcription factor signal transducer and activator of transcription 3 (STAT3) is frequently overexpressed and activated in paclitaxel-resistant breast cancer and is associated with tubulin." (PMID 37242532, 2023). "For example, targeting JAK2/STAT3 signaling pathway has been utilized in breast cancer treatment." (PMID 36836069, 2023). "Finally, STAT3 is constitutively activated in more than 40% of breast cancers and is thought to promote breast tumour progression." (PMID 37193964, 2023). "Research has found that the expression of STAT3 is abnormally high and persistently activated in many human solid tumors and hematoma cells, such as thyroid carcinoma, liver carcinoma, breast carcinoma and pancreatic carcinoma." (PMID 38031104, 2023). "Another critical player of breast cancer metastasis is STAT3 signaling pathway." (PMID 36431925, 2022). "Although further studies involving the assessment of STAT3 inhibition in combination with immunotherapies are needed, the comprehensive crosstalk between STAT3-dependent pathways and immune checkpoints presents an attractive therapeutic target in breast cancer." (PMID 35053592, 2022). "In addition, Stattic inhibited CAA-CM induced phosphorylation of Stat3 in breast cancer MDA-MB-231 and BT549 cells." (PMID 35280694, 2022). "In addition, STAT3–NFkB signaling is known to be activated in breast CSCs and the inhibition of STAT3 in two breast cancer cell lines reduced CD44+ CSC marker cell population." (PMID 35207472, 2022). "The LIF/Stat3 axis induced a massive release of CXCLs from breast cancer cells into their surrounding microenvironment, which is responsible for the uptake of CXCLs by CAA from the microenvironment and the sustained activation of ERK1/2 and its downstream targets, such as NF-κB and Stat3." (PMID 35280694, 2022). "Importantly, there is increasing preclinical and clinical evidence that Stat3 inhibitors reduce breast cancer growth and metastasis, indicating the potential clinical value of measuring Stat3 activity." (PMID 36017196, 2022). "Additionally, nifuroxazide, an antibiotic, exhibits anti-STAT3 activity and suppresses breast cancer tumor growth and lung metastases." (PMID 35371975, 2022). "In addition, previous literature has shown that PDSS1 promotes breast cancer progression through the STAT3 signaling pathway." (PMID 35965499, 2022). "Moreover, breast cancer cell lines with MRE11 overexpression can induce STAT3 phosphorylation at tyrosine-705 and serine-727 residues and promote cancer cell proliferation and migration." (PMID 36547079, 2022). "As both BRK and STAP-2 expression are high in breast cancer cells, their coupling may promote the abnormal activation of STAT3." (PMID 36010693, 2022). "Pentadecanoic acid suppresses the CSC subpopulation through inhibition of IL-6/JAK/STAT3 signaling and increases apoptosis in ER+ breast cancer cell line; however, the exact mechanism remains unknown." (PMID 35371975, 2022). "Our previous study demonstrated that overexpression of BQ could enhance STAT3 signaling by up-regulating the expression of IL-6 to modulate tamoxifen resistance in breast cancer." (PMID 35054486, 2022). "Notably, a new study found that the upregulation of SIR4 enhanced the sensitivity of ER + breast cancer cells to tamoxifen by inhibiting the activation of the STAT3 pathway." (PMID 35154350, 2022). "To further confirm the selectivity of LLL12B in breast cancer cells, we tested its effects on the phosphorylation of STAT3, STAT1, or ERK following the stimulation with IL-6, IFN-γ, or EGF in the T47D breast cancer cells, which express lower basal levels of P-STAT3, and in the MDA-MB-231 TNBC cells." (PMID 36009550, 2022).
breast cancer (continued). "Indeed, MAT1 has been reported to promote breast cancer progression and metastasis by altering signaling pathways, including the activation of STAT3 transcription and repression of SMAD7 transcription to ensure the TGFβ signaling." (PMID 35327559, 2022). "However, many pre-clinical studies have highlighted the potential for such therapies, and a number of clinical trials are currently evaluating safety and efficacy of anti-IL-6/IL-11/STAT3 agents for the treatment of breast cancer." (PMID 35053592, 2022). "Further, the role of STAT-3 pathway in IL-6 mediated CSC enrichment in breast cancer was confirmed by using Stattic, a STAT-3 inhibitor, and it was observed that pre-treatment with Stattic attenuated activated macrophage derived IL-6 mediated CSC enrichment in breast cancer." (PMID 35300689, 2022). "On the other hand, in the luminal breast cancer group, STAT3(−) cases had a poor prognosis." (PMID 35314590, 2022). "The lncRNA-ATB is upregulated by TGF-β to stabilize IL-11 transcripts in hepatocellular cancer cells, and its upregulation is also observed in early metastatic breast cancer cells to promote survival within the metastatic niche via IL-11/STAT3-dependent mechanisms." (PMID 35053592, 2022). "Notably, ectopic ΔCYTL1 expression significantly inhibited breast cancer cell proliferation and invasion, and STAT3 activation slowed the tumor growth and prolonged the survival without pulmonary metastasis in animal models." (PMID 35115484, 2022). "It decreases lung cancer invasion by inhibiting the S100A4/NF-B/MMP9 axis: 350 reduces both the breast cancer cell pulmonary metastases and metastatic potential of lapatinib-resistant breast cancer cells by inhibiting the STAT3-FAK-Src axis and epithelial-mesenchymal transition (EMT), respectively." (PMID 35225948, 2022). "Consistent with this hypothesis, an LMP-promoting role of STAT3 has been documented in several previous studies, for example during mammary gland involution as well as in breast cancer cells treated with a derivative of the natural molecule riccardin D." (PMID 35053502, 2022). "Therefore, it remains pertinent to maintain a homeostatic balance of IL-6/JAK/STAT3 as dysregulation creates a vicious autocrine and paracrine inflammatory loop which promotes breast cancer metastasis and therapeutic resistance." (PMID 35371975, 2022). "Further, expression of IL-6 receptor could have been examined in breast cancer cells for more conclusive demonstration of TAM derived IL-6 mediated activation of STAT-3 pathway in breast cancer cells." (PMID 35300689, 2022). "A study investigated whether Stat3, an oncogene involved in the development of metastatic breast cancer cells, affected the release of ctDNA in mouse blood." (PMID 35628154, 2022). "Furthermore, certain studies have shown that STAT3 and p-STAT3 expression can predict the effect of chemotherapy in breast cancer." (PMID 35314590, 2022). "However, in contrast to ERβ -mediated action, ERα was found to enhance the phospholyation and acetylation of STAT3 in breast cancer cells." (PMID 36207725, 2022). "Interestingly, breast cancer cells can upregulate OPG in BSFs in an IL-6-dependent manner through the IL-6/STAT3 pathway." (PMID 36359766, 2022). "Likewise in previous studies, STAT3 inhibition has been reported to decrease cell proliferation and apoptosis promotion in various cancers including breast cancer." (PMID 36686654, 2022). "Luteolin could enhance paclitaxel-induced apoptosis in human breast cancer MDA-MB-231 cells by blocking STAT3." (PMID 35386215, 2022). "Furthermore, adipocyte-derived IL-6 promotes the spheroid formation of BCSCs by stimulating NF-κB and STAT3 signaling pathways in HER2-positive breast cancer." (PMID 35805056, 2022).